PNPLA2 (patatin like domain 2, triacylglycerol lipase)
Diseases named in the same sentence as PNPLA2 in open-access papers (continued):
Sharing a sentence is not in itself a finding about the gene and the disease.
neutral lipid storage disease (14 papers, 2007 to 2025). Neutral lipid storage disease (NLSD) refers to a group of diseases characterized by a deficit in the degradation of cytoplasmic triglycerides and their accumulation in cytoplasmic lipid vacuoles in most tissues of the body. "Deficiency of adipose triglyceride lipase (ATGL) due to mutation in PNPLA2 causes neutral lipid storage disease with myopathy (NLSDM), an autosomal recessive disorder (MIM: #610717)." (PMID 39119584, 2024). "Patients carrying PNPLA2 mutations that resulted in the loss or decreased function of ATGL develop neutral lipid storage disease with myopathy (NLSDM), an autosomal recessive disorder." (PMID 39119584, 2024). "Neutral lipid storage disease (NLSD) with myopathy (NLSD-M) is a rare autosomal recessive disorder caused by ATGL/PNPLA2 mutations." (PMID 35053204, 2021). "Neutral lipid storage diseases (NLSDs) are genetic disorders caused by mutations in adipose triglyceride lipase (ATGL/PNPLA2) or in α-β hydrolase domain 5 (CGI-58/ABHD5)." (PMID 30795549, 2019). "In humans, mutations in the ATGL gene (PNPLA2) are associated with a rare inherited disorder annotated as neutral lipid storage disease with myopathy (NLSD-M)." (PMID 25890298, 2015). "Previous studies reported that mutations in PNPLA2 could cause neutral lipid storage disease with myopathy (NLSDM)." (PMID 29416711, 2018). "The similarity between mammalian and Drosophila TAG mobilization is underscored by observations involving the brummer (bmm) mutant fly and human neutral lipid storage disease: both are caused by mutations in the gene encoding adipocyte TAG lipase (ATGL, PNPLA2)." (PMID 18081423, 2007).
liposarcoma (10 papers, 2017 to 2023). A usually painless malignant tumor that arises from adipose tissue. "Collectively, these data highlight PNPLA2 as a promising diagnostic and prognostic biomarker that is likely to play a role in liposarcoma pathogenesis." (PMID 32158531, 2020). "Therefore, tissue specific inactivation of Pnpla2 and Lipe causes liposarcoma in mice, and down-regulation of PNPLA2 and LIPE expression occurs in human DDLS." (PMID 28459858, 2017). "For example, in humans, PNPLA2 deletion was found in sarcoma and liposarcoma, and a Pnpla2/Hsl double-knockout mice model developed liposarcoma." (PMID 37780210, 2023). "In respect to the pathogenesis of the disease, our results give a new insight into possible molecular mechanisms involved and support the recent observation that deletion of PNPLA2 is a novel factor in liposarcoma progression." (PMID 32158531, 2020). "Another indication of the direct involvement of PNPLA2 in liposarcoma pathogenesis comes from a recent study where global genome characterization of soft tissue sarcomas was performed." (PMID 32158531, 2020). "Of note, deletion of PNPLA2 is reported in well differentiated liposarcoma and sarcoma." (PMID 28459858, 2017). "This clearly reveals a positive synergistic epistatic interaction between the Pnpla2 and Lipe genes, because neither single lipase deficiency causes liposarcoma." (PMID 28459858, 2017). "In contrast, double knockout of Pnpla2 and Lipe induced liposarcoma in mice, and abnormal expression of G0S2 was observed in double knockout liposarcoma tissues." (PMID 35912266, 2022). "Although PNPLA2 deletion has been reported in well differentiated liposarcoma and LIPE deletion, in DDLS with poor outcome, neither ATGL deficiency nor HSL deficiency reportedly causes liposarcoma in mice." (PMID 28459858, 2017). "Recently, Wu and collaborators demonstrated that double knockouts of PNPLA2 and LIPE in mice, but not their single knockouts, down-regulated metabolic genes, including those involved in fatty acid and lipid metabolism, and the mice spontaneously developed liposarcoma in brown adipose tissue." (PMID 32158531, 2020).
prostate carcinoma (9 papers, 2016 to 2025). A carcinoma that arises from epithelial cells of the prostate gland. "Clarifying both PNPLA2-dependent and -independent roles of ABHD5 in prostate cancer may uncover new insights into how lipid metabolism intersects with oncogenic signaling pathways such as c-MYC." (PMID 41349769, 2025).
Neutral lipid storage disease with myopathy (8 papers, 2016 to 2025). "Neutral lipid storage disease with myopathy (NLSDM) is a rare genetic myopathy caused by mutations in the patatin-like phospholipase domain-containing protein (PNPLA2) gene." (PMID 40598302, 2025). "Neutral lipid storage disease with myopathy (NLSD-M) is an ultra-rare mostly autosomal recessive disorder caused by mutations in the PNPLA2 gene, which encodes adipose triglyceride lipase (ATGL)." (PMID 30223778, 2018). "Triglyceride deposit cardiomyovasculopathy (TGCV) is a phenotype primarily reported in patients carrying genetic mutations in PNPLA2 encoding adipose triglyceride lipase (ATGL) which releases long chain fatty acid (LCFA) as a major energy source by the intracellular TG hydrolysis." (PMID 31186072, 2019). "NLSD includes neutral lipid storage disease with myopathy (NLSDM) and neutral lipid storage disorder with ichthyosis caused by mutations in the patatin-like phospholipase domain-containing protein (PNPLA2) and α/β-hydrolase domain-containing protein 5 (ABHD5) genes, respectively." (PMID 40598302, 2025). "Neutral lipid storage disease with myopathy (NLSD-M) is a rare autosomal recessive disease caused by mutations in the Patatin Like Phospholipase Domain Containing 2 (PNPLA2) gene which encodes adipose triglyceride lipase (ATGL)." (PMID 37106355, 2023). "Neutral lipid storage disease with myopathy (NLSD-M, OMIM #610717) is a rare autosomal recessive disorder caused by mutations in the PNPLA2 gene that maps to chromosome 11, reducing normal expression or function of the ATGL protein and leading to the accumulation of triglycerides in various tissues." (PMID 37239314, 2023).
lipid metabolism disorder (6 papers, 2022 to 2026). "Neutral lipid storage disease with myopathy (NLSDM) is an ultra-rare autosomal recessive lipid metabolism disorder caused by PNPLA2 variants, leading to defective adipose triglyceride lipase (ATGL) function and pathological triglyceride accumulation in multiple tissues." (PMID 42266408, 2026).
liver disease (5 papers, 2019 to 2025). "Silymarin/silybin regulates a significant number of these lipid metabolic genes, including iPLA2/PLA2G6, ATGL/PNPLA2, PLD1, LPIN2, and by trend PNPLA3 (which is a major genetic risk factor for MAFLD 131) and HSD17B13, counteracting the observed dysregulation in liver diseases." (PMID 39897559, 2025).
non-small cell lung carcinoma (5 papers, 2016 to 2022). A group of at least three distinct histological types of lung cancer, including non-small cell squamous cell carcinoma, adenocarcinoma, and large cell carcinoma. "Indeed, a decrease in ATGL protein levels can be observed in cancers such as human non-small cell lung cancer and pancreatic cancer, and Pnpla2 is frequently reported to be absent in these cancer cells." (PMID 35912266, 2022).
pancreatic cancer (5 papers, 2019 to 2023). "On the contrary, another study showed that high expression of PNPLA2 is associated with adiposity and increased tumor stroma in patients with pancreatic cancer." (PMID 34503201, 2021).
colitis (4 papers, 2017 to 2023). Inflammation of the colon. "We, therefore, sought to determine the importance of adipocyte lipolysis during DSS‐induced colitis by deleting the cytoplasmic lipase Pnpla2/Atgl, a rate‐limiting enzyme in the lipolytic pathway." (PMID 36795015, 2023).
non-alcoholic fatty liver disease (4 papers, 2015 to 2025). "PNPLA2 is a susceptibility gene of nonalcoholic fatty liver disease (NAFLD) in an obese population." (PMID 32685558, 2020).
Stroke (4 papers, 2017 to 2024). Sudden impairment of blood flow to a part of the brain due to occlusion or rupture of an artery to the brain. "Based on the Gene Expression Omnibus (GEO) database analysis, significant differences in the expression levels of LIPC, APOB, CETP, PNPLA2, and LMF1 between the control and stroke groups were observed." (PMID 37273686, 2023). "Our bioinformatics analysis results indicated that the expression levels of LIPC and its related genes (APOB, CETP, PNPLA2, and LMF1) showed significant differences between stroke and control groups." (PMID 37273686, 2023). "Furthermore, bioinformatics analysis results demonstrated that the expression levels of LIPC and its related genes (APOB, CETP, PNPLA2, and LMF1) were significantly different between the control and stroke groups (p < 0.05), and LIPC-related proteins were mainly related to lipid metabolism." (PMID 37273686, 2023).
endotoxemia (3 papers, 2024 to 2025). "Interestingly, expression of the 2-AG biosynthesizing (and key lipase-encoding) enzyme, PNPLA2, was downregulated upon LPS exposure, suggesting bovine adipocytes may exhibit a reduced capacity to synthesize the metabolically active compound 2-AG during endotoxemia." (PMID 39095900, 2024).
glaucoma (3 papers, 2015 to 2025). Increased pressure in the eyeball due to obstruction of the outflow of aqueous humor. "Notably, PEDF secretion is enhanced in both glaucoma and retinal cell models in response to zinc stress; however, zinc binding negatively affects axogenic, differentiative and prosurvival functions of PEDF by suppressing its ability to activate receptor PEDF-R/PNPLA2." (PMID 40596696, 2025).
cardiac ischemia (2 papers, 2022 to 2026). "To further investigate the underlying cause for decreased adipocyte size in iWAT after cardiac ischemia, we analyzed gene expression of the main lipolytic enzyme ATGL (Pnpla2)." (PMID 36388122, 2022).
retinal degeneration (2 papers, 2021 to 2023). Degeneration of the retina. "Because phospholipids are the most abundant lipid class in the retina, we investigated the role of PEDF-R in photoreceptors by generating CRISPR Pnpla2 knock-out mouse lines in a retinal degeneration-free background." (PMID 36934843, 2023). "Recently, we generated a cKO mouse with a targeted deletion of the Pnpla2 gene in the RPE, which is in a retinal degeneration rd8-free background." (PMID 36934843, 2023). "The lack of photoreceptor dysfunction with RPE lipid accumulation due to PNPLA2 downregulation also suggests that during development a compensatory mechanism independent of Pnpla2/PEDF-R is likely to be activated, thereby minimizing retinal degeneration in the cKO mouse." (PMID 33605986, 2021).
soft tissue sarcoma (2 papers, 2017 to 2020). A malignant neoplasm arising from muscle tissue, adipose tissue, blood vessels, fibrous tissue, or other supportive tissues excluding the bones. "The loss of chromosome 11p15.5 harboring PNPLA2 was significantly associated (p < 0.01, chi-square) with soft tissue sarcomas." (PMID 28459858, 2017). "In addition, copy number analysis for 265 patients with soft tissue sarcoma from the TCGA dataset was performed to test the hypothesis that PNPLA2 and LIPE might be tumor suppressors in some tissues." (PMID 28459858, 2017).
Blindness (1 paper, 2023). Blindness is the condition of lacking visual perception defined as a profound reduction in visual perception. "In summary, the findings demonstrate a role for PNPLA2 in photoreceptor survival and function and underscore phospholipid metabolism as a potential therapeutic target for some forms of blindness." (PMID 36934843, 2023). "Deletion of the Pnpla2 gene in mice may prove useful to understand the role of PEDF-R, and phospholipids, in the survival of photoreceptors to prevent blindness." (PMID 36934843, 2023).
congenital heart disease (1 paper, 2024). A heart disease that is present at birth. "TGCV is congenital heart disease associated with mutations in the Patatin-like phospholipase domain containing protein 2 (PNPLA2) gene encoding adipose triglyceride lipase (ATGL)." (PMID 38706718, 2024).
congenital myotonia (1 paper, 2023). Myotonia congenita (MC) is a genetic neuromuscular channelopathy which usually presents in early childhood resulting in a delay of skeletal muscle relaxation following contraction. "We will report a rare case of association of pathogenic variants on PNPLA2 and CLCN1 genes with a mixed phenotype of NLSD-M and a subclinical form of Thomsen’s congenital myotonia." (PMID 37106355, 2023).
COVID-19 (1 paper, 2021). A disease caused by infection with severe acute respiratory syndrome coronavirus 2. "Corresponding to the top metabolic PheWAS traits related to fat metabolism, one distinct COVID-19 hg-replicated SNP was a genome-wide significant e/sQTL of PNPLA2, a critical enzyme involved in the first step of triglyceride hydrolysis." (PMID 34027315, 2021).
dilated cardiomyopathy (1 paper, 2024). Cardiomyopathy which is characterized by dilation and contractile dysfunction of the left and right ventricles. "We reported two male patients carrying a homozygous splicing mutation NM_020376.4 (c.757 + 1G>T) in PNPLA2, presenting with severe dilated cardiomyopathy and mild skeletal muscle involvement." (PMID 39119584, 2024).
distal hereditary motor neuropathy type 2 (1 paper, 2024). "We propose that KCNMB1, MYH11, TAGLN, and PNPLA2 are novel genes in Distal Hereditary Motor Neuropathy type 2." (PMID 39480826, 2024). "KCNMB1, MYH11, PNPLA2, and TAGLN linked to Distal Hereditary Motor Neuropathy type 2." (PMID 39480826, 2024).
dry eye (1 paper, 2022). "In addition, the beneficial effects of the 29-mer on EDE depend on PEDF-R/PNPLA2, implying a critical role of PNPLA2 on the amelioration of inflammatory responses in the dry eye milieus stimulated by PEDF." (PMID 36201200, 2022).
lipoma (1 paper, 2020). A benign, usually painless, well-circumscribed lipomatous tumor composed of adipose tissue. "The expression of both LIPE and PNPLA2 showed a gradual decrease from lipomas towards DDLPS, with significantly lower expression already in WDLPS/ALT compared to lipomas." (PMID 32158531, 2020).
malaria (1 paper, 2020). Malaria is a serious and sometimes fatal disease caused by a parasite that commonly infects a certain type of mosquito which feeds on humans. "To test if natural genetic variation in PNPLA2 affects susceptibility to malaria LS infection, we obtained two NLSDM patient dermal fibroblast lines F121-12N-YC280270 and F122-12N-LB141159 carrying mutation in exon 5 (613dupC) and exon 8 (1051delC), respectively." (PMID 32442532, 2020).
myopia (1 paper, 2023). "The PNPLA2 gene is highly expressed in all eye tissues, including the cornea, and is differentially expressed in the corneal epithelium in patients with KC and myopia." (PMID 38136930, 2023).
Myotonia (1 paper, 2023). An involuntary and painless delay in the relaxation of skeletal muscle following contraction or electrical stimulation. "Here, we describe a patient with chronic proximal myopathy, subtle clinical myotonia and electrical myotonia on electromyography (EMG) related to both pathogenic variants on PNPLA2 and CLCN1 genes." (PMID 37106355, 2023).
cancer (102 papers, 2013 to 2025). A tumor composed of atypical neoplastic, often pleomorphic cells that invade other tissues. "The results of pan-cancer analysis in this study describe the expression levels of four genes (Irs2, Plin2, Pnpla2 and Srebf2) in various types of cancerous tissues compared to normal tissues." (PMID 37047411, 2023). "Development of drugs that disrupt HIG2-PNPLA2 interaction would liberate PNPLA2 and potentiate FA oxidation-driven ROS production to toxic levels, resulting in apoptotic death of hypoxic cancer cells." (PMID 31092908, 2019). "Notably, our series of studies gradually revealed the PNPLA2-independent roles of ABHD5 in the cancer field." (PMID 34795238, 2021). "Hence, inhibition of PNPLA2 activity by HIG2 under conditions of hypoxia also promotes cancer cell survival by reducing FA oxidation, ROS overproduction and oxidative damage." (PMID 31092908, 2019). "Although no causative molecular mechanisms for ATGL downregulation has been revealed yet, it is noteworthy to mention that the 11p15.5 chromosome arm harbouring the human PNPLA2 gene results frequently deleted in cancer and considered a hot-spot of cytogenetic alterations in human malignancies." (PMID 29472527, 2018). "Machine learning models based on seven LM-related genes (CHEK2, LIPT1, TUFM, NDUFA10, AGK, PNPLA2, and GFM1) accurately predicted immunotherapy outcomes for multiple cancer types, including LUSC, and outperformed other currently known biomarkers." (PMID 40568577, 2025). "Nowadays, there are many studies on the role of ATGL in cancer, but there is a lack of studies on transcriptional factors that target the PNPLA2 promoter in tumor cells." (PMID 36604676, 2023). "Nowadays, there are many studies on the role of ATGL in cancers, but there is a lack of studies on transcription factors that target Pnpla2 on the changes in the ubiquitination process of ATGL in tumor cells." (PMID 35912266, 2022). "Fatty acid oxidation is also reported to be deregulated in cancer cells, and, in this scenario, sTWEAK might upregulate this lipolytic process by increasing CPT1 expression in the mitochondria and PNPLA2 expression in the cytoplasm, both reported to be deregulated in PCa." (PMID 34572917, 2021). "Similarly, a recent review considers non-energetic tumor-suppressive functions of PNPLA2 in cancer." (PMID 32158531, 2020). "In contrast, deletion of PNPLA2 did not affect proliferation and colony formation, further supporting a unique role for ABHD5 in suppressing cancer cell aggressiveness." (PMID 41349769, 2025). "Unlike normal cells, which use the protein PNPLA2 (or ATGL) to release fatty acids from these droplets for energy, cancer cells block this release with the help of a protein called hypoxia-inducible gene 2 (HIG2)." (PMID 39596452, 2024).